DPYSL5 (dihydropyrimidinase like 5)
Description:
Involved in the negative regulation of dendrite outgrowth.
Synonyms: CRAM; CRMP-5; CRMP5; ULIP6; CV2; RTSC4
Tractability: PROTAC: its protein half-life has been measured.
Gene: Protein-coding gene on chromosome 2 (26,847,747 to 26,950,351, forward strand). Ensembl gene ENSG00000157851.
Subcellular location: Cytoplasm
Subcellular location (Human Protein Atlas): Nucleoplasm; Cytosol
Pathways (Reactome):
Developmental Biology: CRMPs in Sema3A signaling
Gene Ontology:
Molecular function: protein binding; dihydropyrimidinase activity; hydrolase activity; hydrolase activity, acting on carbon-nitrogen (but not peptide) bonds
Biological process: negative regulation of dendrite morphogenesis; axon guidance; nervous system development; pyrimidine nucleobase catabolic process; signal transduction; neuron differentiation
Cellular component: cytosol; cytoplasm; dendrite; glutamatergic synapse; neuronal cell body; protein-containing complex; synapse
Genetic constraint (gnomAD): Loss-of-function variants: 8 observed, 53.8 expected, observed/expected ratio (o/e) 0.15, 90% interval 0.086 to 0.27. The upper end of that interval is the gene's LOEUF score, 0.27, which puts it in group 1 of 6, group 1 being the genes least tolerant of losing a copy. Missense variants: 453 observed, 729.77 expected, observed/expected ratio (o/e) 0.62, 90% interval 0.57 to 0.67. Synonymous variants: 261 observed, 289.94 expected, observed/expected ratio (o/e) 0.9, 90% interval 0.81 to 1.
Homologues: Orthologues: macaque DPYSL5 (100% identical), chimpanzee DPYSL5 (99% identical), pig DPYSL5 (99% identical), dog DPYSL5 (99% identical), rabbit DPYSL5 (98% identical), mouse Dpysl5 (98% identical), rat Dpysl5 (98% identical), guinea pig DPYSL5 (88% identical), tropical clawed frog dpysl5 (85% identical), zebrafish dpysl5a (80% identical), zebrafish dpysl5b (76% identical), Caenorhabditis elegans unc-33 (35% identical). Paralogues in human: DPYS (53% identical), DPYSL2 (52% identical), CRMP1 (51% identical), DPYSL3 (51% identical), DPYSL4 (49% identical).
Diseases named in the same sentence as DPYSL5 in open-access papers:
DPYSL5 is named in the same sentence as 126 diseases in open-access papers, as found by Europe PMC text mining. Sharing a sentence is not in itself a finding about the gene and the disease. The quoted sentences say what the papers report.
lung carcinoma (9 papers, 2011 to 2025). "Through our analysis, we also found other eight proteins (ACAT2, PSIP1, TCERG1, DPYSL5, TUBA1A, AKR1B1, ANP32E, and TXNDC17) that have been associated with other cancers, but not in lung cancer." (PMID 32351780, 2020).
glioblastoma (6 papers, 2014 to 2024). The most malignant astrocytic tumor (WHO grade IV). "In glioblastoma, DPYSL5 has been previously shown to protect Notch receptors from E3 ubiquitin ligase Itch-mediated lysosomal degradation, leading to sustained Akt activation." (PMID 38238517, 2024).
epilepsy (4 papers, 2017 to 2025). A brain disorder characterized by episodes of abnormally increased neuronal discharge resulting in transient episodes of sensory or motor neurological dysfunction, or psychic dysfunction. "These suggest that DPYSL5 may function in CCD with epilepsy via affecting BDNF and CRMP2." (PMID 28222113, 2017). "Increased expression of DPYSL5 can regulate dendritic development by mediating BDNF signaling in the central nervous system and modulate the function of CRMP2 by interacting with tubulin, thus affect the cytoskeleton remodeling, which is important in CCD with epilepsy." (PMID 28222113, 2017).
prostate carcinoma (3 papers, 2014 to 2024). A carcinoma that arises from epithelial cells of the prostate gland. "We hypothesize that the AR/DPYSL5/EZH2/PRC2 axis is a novel mechanism underlying prostate cancer progression to t-NEPC, and it is important to further elucidate the theranostic potential of DPYSL5 and explore any pharmacological strategies that could manipulate its expression." (PMID 38238517, 2024). "The results showed that DPYSL5 overexpression leads to a significant induction of neurite length and branch points in LNCaP as well in C42B and VCaP prostate cancer cells when compared to control (CTRL) cells." (PMID 38238517, 2024). "Based on these results, DPYSL5 expression is required for prostate cancer cell proliferation and for the cells to progress further from G1-phase, especially under ADT." (PMID 38238517, 2024). "Given that DPYSL5 is a regulator of neural development and regeneration, we here explored its potential role in prostate cancer antiandrogen resistance and t-NEPC plasticity." (PMID 38238517, 2024). "In conclusion, DPYSL5 plays a critical role in regulating prostate cancer cell plasticity, and we propose the AR/DPYSL5/EZH2/PRC2 axis as a driver of t-NEPC progression." (PMID 38238517, 2024). "To investigate DPYSL5 expression in prostate cancer tumors, we examined RNA-seq data from various prostate adenocarcinoma patient cohorts, including tumors with neuroendocrine differentiation." (PMID 38238517, 2024). "DPYSL5 overexpression in prostate cancer cells induces a neuron-like phenotype, enhances invasion, proliferation, and upregulates stemness and neuroendocrine-related markers." (PMID 38238517, 2024). "Our results suggest that DPYSL5 may play an important role in t-NEPC development and that DPYSL5 expression is required for prostate cancer cell survival under androgen deprivation, making it an interesting and potential target for drug development." (PMID 38238517, 2024). "In addition to what has been previously shown for neurons, these results collectively indicate that DPYSL5 can induce neurite-like structures not only in neuronal tissue but also in prostate cancer cells." (PMID 38238517, 2024). "Moreover, DPYSL5 overexpression increased the expression of neuronal lineage markers and induced neuron-like morphology in prostate cancer cells and chick chorioallantoic membrane (CAM) tumors." (PMID 38238517, 2024). "Mechanistically, DPYSL5 promotes prostate cancer cell plasticity via EZH2-mediated PRC2 activation." (PMID 38238517, 2024). "Androgen receptor (AR) suppresses DPYSL5, and overexpression of DPYSL5 promotes prostate cancer cell plasticity via EZH2-mediated PRC2 activation, suggesting that the AR/DPYSL5/EZH2/PRC2 axis may act as a driver of treatment-induced neuroendocrine prostate cancer." (PMID 38238517, 2024). "However, as of now, the involvement of DPYSL5 in prostate cancer remains unexplored." (PMID 38238517, 2024). "As AR inhibitor ENZ is known to induce t-NEPC, we first exposed LNCaP and C42B prostate cancer cells to ENZ and monitored the expression of DPYSL5 and neuronal lineage markers every three days over a total of twelve days." (PMID 38238517, 2024). "To this end, we analyzed DPYSL5 expression in patient samples using our unique CRPC-NEPC cohort, which includes 135 prostate cancer patient samples, encompassing 55 t-NEPC patient samples." (PMID 38238517, 2024). "Given the involvement of DPYSL5 in axon guidance and neurite outgrowth, and our observation that ENZ induces DPYSL5 expression, we analyzed the morphological changes in ENZ-exposed prostate cancer cells using IncuCyte S3 live-cell imaging." (PMID 38238517, 2024). "The DPYSL5 protein staining intensity significantly correlated with SYP, CGA and NCAM in prostate cancer patients and showed an inverse correlation with AR and PSA." (PMID 38238517, 2024).
prostate carcinoma (continued). "On molecular level, we demonstrated that DPYSL5 expression is under AR regulation, and the NE phenotype is inducible with the clinically used second -generation AR inhibitor Enzalutamide (ENZ) in prostate cancer cells." (PMID 38238517, 2024).
brain malformations (2 papers, 2023 to 2025). "We thus expanded the functional characterization of DPYSL5 variants in NDD with brain malformations, including at the fetal stage, highlighting a fundamental role of the DPYSL5 gene in brain formation and functioning." (PMID 41286434, 2025). "We collected clinical data on individuals in whom DPYSL5 missense variants were identified through clinical genetic assessment of NDD or following the identification of brain malformations in fetuses." (PMID 41286434, 2025). "Neurodevelopmental disorders (NDD) with brain malformations have recently been associated with de novo variants in the DPYSL5 gene, which encodes a member of the dihydropyrimidinase-like proteins family." (PMID 41286434, 2025).
glaucoma (2 papers, 2019 to 2025). Increased pressure in the eyeball due to obstruction of the outflow of aqueous humor. "The role of DPYSL5 is implicated in axonal guidance, and its mRNA expression is downregulated in early glaucoma." (PMID 40076480, 2025). "While DPYSL3 is involved in glaucoma, dihydropyrimidinase-related protein 5 (DPYSL5) has little information regarding its role in ocular diseases." (PMID 40076480, 2025).
cortical dysplasia (1 paper, 2017). "And FSCN1, CRMP1, NDRG1, DPYSL5, MAP4, and FABP3 were selected for validation and identified to be increased in childhood cortical dysplasia patients, while PRDX6 and PSAP were identified decreased." (PMID 28222113, 2017).
diabetes (1 paper, 2022). "DPYSL5 (rs1371614) has been associated with diabetes and GDM." (PMID 36313769, 2022).
ischemic stroke (1 paper, 2015). A stroke disorder caused by obstruction of blood flow to the brain, due to thrombotic (local blood clot formation) or embolic (due to a blood clot or other material traveling from another site) event. "Taken together, our results suggest that the upregulation of Clu, Dpysl5, and Cat is associated with a self-compensation mechanism against ischemic stroke." (PMID 26492191, 2015).
Rett syndrome (1 paper, 2021). A severe neurodevelopmental disorder affecting the central nervous system.
Ritscher-Schinzel syndrome (1 paper, 2024). "Ritscher-Schinzel syndrome is a developmental disorder characterized by abnormal craniofacial, cerebellar, and cardiovascular malformations, classically associated with WASHC5 and CCDC22 but more recently with VPS35L and DPYSL5 being implicated as well." (PMID 39282277, 2024).
cancer (22 papers, 2011 to 2025). A tumor composed of atypical neoplastic, often pleomorphic cells that invade other tissues. "DPYSL5 overexpression also led to increased mRNA expression of Nanog, SOX2, NSE, CGA, and ASCL1, suggesting that cells achieve characteristic of neuron-like cancer progenitor cells, possibly through the activation of EZH2." (PMID 38238517, 2024).
tumor (18 papers, 2010 to 2026). "The results revealed that cells overexpressing DPYSL5 showed a neurite-like morphology with long neurite-like protrusions in the tumor." (PMID 38238517, 2024). "Moreover, we conducted a spheroid invasion assay using Matrigel and IncuCyte S3 live-cell imaging to determine if DPYSL5 overexpression is capable of inducing invasion in 3D tumor spheroids." (PMID 38238517, 2024). "We then performed DPYSL5 IHC staining also for patient PDX tumor cohort." (PMID 38238517, 2024). "Our unique CRPC-NEPC cohort, comprising 135 patient tumor samples, including 55 t-NEPC patient samples, exhibits a high expression of DPYSL5 in t-NEPC patient tumors." (PMID 38238517, 2024). "DPYSL5, NCAM, CGA, SYP and AR protein expressions were evaluated in the tumor tissue samples using immunohistochemistry (IHC)." (PMID 38238517, 2024).
neurodevelopmental disorder (2 papers, 2025). A behavioral and cognitive disorder with onset during the developmental period that involves impaired or aberrant development of intellectual, motor, or social functions. "Another gene, dpysl5b (DPYSL5 in human), a member of the collapsing response mediator protein family, is involved in neural development, and missense mutation in human could cause neurodevelopmental disorder." (PMID 39083243, 2025).
DPYSL5 also shares sentences with these, for which no sentence is quoted: encephalitis (24 papers); thymoma (18); small cell lung carcinoma (17); cerebellar ataxia (13); paraneoplastic neurological syndrome (12); optic neuritis (11); autoimmune encephalitis (8); Chorea (7); peripheral neuropathy (7); uveitis (7); Ataxia (5); Autoimmunity (5); encephalomyelitis (5); Myelopathy (5); Optic neuropathy (5); breast carcinoma (4); cranial neuropathies (4); Encephalopathy (4); myasthenia gravis (4); neurological diseases (4); Parkinsonism (4); retinopathy (4); Cognitive impairment (3); Alzheimer disease (2); autoimmune optic neuritis (2); cancer-associated retinopathy (2); cognitive decline (2); Dyskinesia (2); glioma (2); Hodgkins lymphoma (2).
A further 82 diseases each share a sentence with DPYSL5 in 2 papers or fewer.